TIMM23 (translocase of inner mitochondrial membrane 23)
Description:
Essential component of the TIM23 complex, a complex that mediates the translocation of transit peptide-containing proteins across the mitochondrial inner membrane. Has a role in the activation of stress-induced mitophagy by protecting PINK1 from OMA1-mediated degradation and facilitating its accumulation at the outer mitochondrial membrane in response to depolarization.
Synonyms: TIM23
Tractability: Antibody: UniProt predicts a signal peptide or a membrane-spanning region. PROTAC: ubiquitination databases record sites on it; its protein half-life has been measured.
Gene: Protein-coding gene on chromosome 10 (45,972,486 to 46,004,338, forward strand). Ensembl gene ENSG00000265354.
Subcellular location: Mitochondrion inner membrane
Subcellular location (Human Protein Atlas): Mitochondria
Pathways (Reactome):
Protein localization: Mitochondrial protein import
Gene Ontology:
Molecular function: protein binding; protein transmembrane transporter activity; transmembrane transporter activity
Biological process: type 2 mitophagy; intracellular protein transport; protein import into mitochondrial matrix
Cellular component: mitochondrial inner membrane; mitochondrial intermembrane space; mitochondrion; TIM23 mitochondrial import inner membrane translocase complex
Genetic constraint (gnomAD): Loss-of-function variants: 14 observed, 27.41 expected, observed/expected ratio (o/e) 0.51, 90% interval 0.34 to 0.8. The upper end of that interval is the gene's LOEUF score, 0.8, which puts it in group 3 of 6, group 1 being the genes least tolerant of losing a copy. Missense variants: 195 observed, 261.86 expected, observed/expected ratio (o/e) 0.74, 90% interval 0.66 to 0.84. Synonymous variants: 76 observed, 95.12 expected, observed/expected ratio (o/e) 0.8, 90% interval 0.66 to 0.97.
Homologues: Orthologues: chimpanzee TIMM23 (100% identical), macaque TIMM23 (100% identical), mouse Timm23 (97% identical), rat Timm23-ps8 (96% identical), rat Timm23b (89% identical), rat Timm23 (88% identical), tropical clawed frog timm23 (81% identical), zebrafish timm23a (71% identical), zebrafish timm23b (64% identical), Drosophila melanogaster Tim23 (36% identical), Caenorhabditis elegans timm-23 (8% identical). Paralogues in human: TIMM23B (79% identical).
Diseases named in the same sentence as TIMM23 in open-access papers:
TIMM23 is named in the same sentence as 29 diseases in open-access papers, as found by Europe PMC text mining. Sharing a sentence is not in itself a finding about the gene and the disease. The quoted sentences say what the papers report.
Alzheimer disease (2 papers, 2023). A progressive, neurodegenerative disease characterized by loss of function and death of nerve cells in several areas of the brain leading to loss of cognitive function such as memory and language. "For instance, accumulated amyloid precursor protein (APP) within mitochondria from individuals with Alzheimer's disease interacts with the protein channel components of both outer and inner membranes: TOM40 and TIM23 (TOMM40 and TIMM23)." (PMID 37303235, 2023).
bladder cancer (2 papers, 2024 to 2025). "As shown, TIMM23 protein expression is not significantly different between epithelial cells and primary/immortalized bladder cancer cells." (PMID 38467612, 2024).
lung carcinoma (2 papers, 2025). "Utilizing TCGA-LUAD and TCGA-LUSC lung cancer datasets, a correlation analysis of TIMM23 was conducted." (PMID 40082395, 2025). "Existing literature indicates a high frequency of the TIMM23-PARGP1 fusion gene in lung cancer, suggesting its functional role in cancer." (PMID 41285805, 2025). "A comprehensive analysis of integrated lung cancer single-cell RNA sequencing (scRNA) data revealed a distinct expression pattern of TIMM23 across various cell types." (PMID 40082395, 2025).
lung squamous cell carcinoma (2 papers, 2025). "In TIMM23-knockdown human embryonic kidney 293 T (HEK293T) cells, undegraded PINK1 accumulated, whereas TIMM23 expression remained unchanged in lung squamous cell carcinoma cell lines H226 and H520 despite variations in BRF2 and SLC8A3 levels." (PMID 40610422, 2025). "First, The Cancer Genome Atlas (TCGA) datasets shows TIMM23 expression levels in normal lung tissues, lung adenocarcinoma (LUAD) tissues, and lung squamous cell carcinoma (LUSC) tissues." (PMID 40082395, 2025).
ovarian carcinoma (2 papers, 2019 to 2024). A malignant neoplasm originating from the surface ovarian epithelium. "Undoubtedly, the relevance of mitochondrial content for therapy response is evidenced by RNA expression analyses available in TCGA-OV data that show superior overall survival of ovarian cancer patients with high expression of the mitochondrial proteins TFAM and TIMM23." (PMID 31699970, 2019).
viral infection (2 papers, 2016 to 2020). "According to antibodies available, we performed Western blot to verify protein changes in HPAEpiC cells and the result showed NDUFA4 and TIMM23 were indeed down-regulated after viral infection." (PMID 33293527, 2020).
breast tumor (1 paper, 2019). "Intriguingly, immunostaining showed that the hypoxia marker GLUT1 and the mitochondria marker TIMM23 had an inverse expression pattern in spontaneous breast tumor tissues." (PMID 30833558, 2019).
epilepsy (1 paper, 2022). A brain disorder characterized by episodes of abnormally increased neuronal discharge resulting in transient episodes of sensory or motor neurological dysfunction, or psychic dysfunction. "Our results show that LC3 B level were significantly increased and TOMM20 and TIMM23 were significantly decreased in the epilepsy model, which indicates an enhanced level of mitophagy in our epileptic mice inducing by KA injection." (PMID 36618822, 2022).
glioma (1 paper, 2022). A benign or malignant brain and spinal cord tumor that arises from glial cells (astrocytes, oligodendrocytes, ependymal cells). "We found that TIMM44 mRNA and protein as well as the YME1L protein levels were significantly increased in OE-YME1L glioma cells, whereas TIMM23 mRNA was unchanged." (PMID 36438483, 2022). "TIMM23 protein levels were indifferent between glioma tissues and normal brain tissues." (PMID 36438483, 2022). "In OE-TIMM44 P1 glioma cells TIMM44 mRNA and protein levels were indeed dramatically increased and TIMM23 expression was unchanged." (PMID 36438483, 2022). "TIMM23 and VDAC1 protein expression was equivalent between astrocytes and glioma cells." (PMID 36438483, 2022). "As compared to the vector control cells (“Vec”), TIMM44 mRNA, but not TIMM23 mRNA, was increased in OE-TIMM44 glioma cells." (PMID 36438483, 2022).
cancer (7 papers, 2019 to 2025). A tumor composed of atypical neoplastic, often pleomorphic cells that invade other tissues. "Dot plots and expression density plots demonstrated a preferential expression of TIMM23 in cancer cells, fibroblasts, and endothelial cells." (PMID 40082395, 2025). "Within the cancer cell cluster, TIMM23 expression was significantly elevated compared to normal lung tissue." (PMID 40082395, 2025). "Single-cell RNA sequencing data further corroborated these findings, demonstrating elevated TIMM23 expression within the cancer cells of NSCLC mass." (PMID 40082395, 2025). "Our findings not only establish TIMM23 as a potential therapeutic target in OS but also provide mechanistic insights that may inform immunotherapy strategies across diverse cancer types." (PMID 41285805, 2025). "We found that erastin or RSL3 or IR treatment increased mitophagy in a time‐ and concentration‐dependent manner in HCT116 and MDA‐MB‐231 cancer cells, as shown by decreased protein levels of the mitochondrial proteins TOM20 and TIMM23 and decreased mitochondrial DNA (mtDNA)." (PMID 39679775, 2025).
tumor (6 papers, 2010 to 2025). "Single-cell transcriptomic data further corroborated these findings, demonstrating elevated TIMM23 expression within the NSCLC tumor cells." (PMID 40082395, 2025). "On the other hand, compared to the TIMM23-KO + oe-NC/TIMM23-KO + oe-NC + Dox groups, the TIMM23-KO + TIMM23-PARGP1-FLAG/TIMM23-KO + TIMM23-PARGP1-FLAG + Dox groups exhibited accelerated tumor growth in tissues." (PMID 41285805, 2025). "Subsequent analysis of tumor tissues revealed depleted TIMM23 expression, ATP reduction, oxidative damage, proliferative arrest, and apoptotic induction." (PMID 40082395, 2025). "The results demonstrated that compared to the TIMM23-WT + oe-NC/TIMM23-WT + oe-NC + Dox groups, the TIMM23-KO + oe-NC/TIMM23-KO + oe-NC + Dox groups showed inhibited tumor growth in tissues." (PMID 41285805, 2025). "In vivo experiments further confirmed the role of TIMM23 in promoting M2 polarization and fusion gene expression, leading to increased chemoresistance and tumor growth." (PMID 41285805, 2025). "Quantitative PCR (qPCR) analysis revealed a substantial elevation in TIMM23 mRNA levels within NSCLC tumor tissues relative to corresponding normal lung epithelia." (PMID 40082395, 2025). "The results showed that compared to the TIMM23-WT + oe-NC/TIMM23-WT + oe-NC + Dox groups, the TIMM23-KO + oe-NC/TIMM23-KO + oe-NC + Dox groups exhibited a significantly lower percentage of Ki67-positive cells in tumor tissues." (PMID 41285805, 2025). "Comparisons of tumor volume and weight among the groups showed that the TIMM23-KO + oe-NC/TIMM23-KO + oe-NC + Dox groups had significantly reduced tumor volume and weight compared to the TIMM23-WT + oe-NC/TIMM23-WT + oe-NC + Dox groups." (PMID 41285805, 2025). "In contrast, the TIMM23-KO + TIMM23-PARGP1-FLAG/TIMM23-KO + TIMM23-PARGP1-FLAG + Dox groups exhibited significantly increased tumor volume and weight compared to the TIMM23-KO + oe-NC/TIMM23-KO + oe-NC + Dox groups." (PMID 41285805, 2025). "In comparison, the TIMM23-KO + TIMM23-PARGP1-FLAG/TIMM23-KO + TIMM23-PARGP1-FLAG + Dox groups showed a significantly higher percentage of Ki67-positive cells in tumor tissues." (PMID 41285805, 2025). "In vivo, silencing of TIMM23 using target shRNA significantly suppressed tumor growth in a xenograft mouse model, underscoring its critical role in NSCLC pathogenesis." (PMID 40082395, 2025). "We further demonstrated a positive correlation between TIMM23 expression and tumor stage, with higher expression levels observed in advanced-stage LUAD & LUSC tumors, including T3/T4 stage tumors, N2/N3 tumors, and Stage III-IV tumors." (PMID 40082395, 2025). "In conclusion, TIMM23 enhances OS chemoresistance and tumor progression by promoting M2 macrophage polarization via mitophagy and upregulating TIMM23-PARGP1 fusion gene expression." (PMID 41285805, 2025). "Based on this, we speculate that under TIMM23-driven M2 polarization, TIMM23-PARGP1 expression in tumor cells may enhance their adaptability to immune signaling and chemotherapeutic stress, exacerbating resistance." (PMID 41285805, 2025). "This suggests that TIMM23 may reshape the immune microenvironment to provide a more supportive niche for tumor cells to acquire a resistant phenotype." (PMID 41285805, 2025). "Additionally, the potential roles of TIMM23 in tumor immunotherapy can be further investigated, exploring its potential as a targeted therapy." (PMID 41285805, 2025). "Interestingly, we found that the majority of them were markedly upregulated in tumor tissues compared with control samples from unaffected patients and normal tissues adjacent to the tumor, with TIMM23 and TIMM17B exhibiting the most pronounced shift in expression." (PMID 38837610, 2024). "First, Western blotting analysis revealed that compared to the TIMM23-WT + oe-NC + Dox group, the TIMM23-KO + oe-NC + Dox group exhibited significantly decreased expression of both TIMM23 and TIMM23-PARGP1 in tumor tissues." (PMID 41285805, 2025).
tumor (continued). "Compared to the TIMM23-KO + oe-NC + Dox group, the TIMM23-KO + TIMM23-PARGP1-FLAG + Dox group showed no significant change in TIMM23 expression but a significant increase in TIMM23-PARGP1 expression in tumor tissues." (PMID 41285805, 2025). "Expression levels of TIMM23, the next closest gene to the risk locus and 1.4 kb telomeric to NCOA4, are not correlated with genotype status in either normal or tumor tissue." (PMID 21085629, 2010).
TIMM23 also shares sentences with these, for which no sentence is quoted: infection (3 papers); Parkinson disease (3); Huntington disease (2); osteosarcoma (2); asbestosis (1); breast carcinoma (1); cardiomyopathy (1); colorectal adenocarcinoma (1); colorectal cancer (1); dilated cardiomyopathy (1); hepatocellular carcinoma (1); lung adenocarcinoma (1); mitochondrial disease (1); mitochondrial protein import disorder (1); neuroblastoma (1); neurodegenerative disease (1); Sengers syndrome (1); testis cancer (1).